ABCB1 (ATP binding cassette subfamily B member 1)
Diseases named in the same sentence as ABCB1 in open-access papers (continued):
Sharing a sentence is not in itself a finding about the gene and the disease.
breast carcinoma (continued). "Since statin use is common in breast cancer patients, it would be of interest to further elucidate the clinical impact of the ABCB1 genotype in breast cancer." (PMID 30370250, 2018). "In summary, results indicated that FTH1P3 silencing suppressed the tumour growth of paclitaxel‐resistant breast cancer cells and ABCB1 protein in vivo." (PMID 29971911, 2018). "In this exploratory study, patients who were ABCB1 homozygous 3435TT-carriers and used statins preoperatively had worse outcomes than other breast cancer patients." (PMID 30370250, 2018). "FTH1P3 promotes the paclitaxel resistance in human breast cancer tumorigenesis by targeting miR‐206/ABCB1 axis, suggesting the novel molecular mechanism of breast cancer chemotherapy resistance." (PMID 29971911, 2018). "In vivo, xenograft mice assay showed that FTH1P3 silencing suppressed the tumour growth of paclitaxel‐resistant breast cancer cells and ABCB1 protein expression." (PMID 29971911, 2018). "Together, these studies demonstrated that taxane-induced CCL20 activated NF-κB through PKCζ or p38 and then promoted the expression of ABCB1, leading to the chemoresistance of breast cancer cells." (PMID 30052635, 2018). "Second, two patients acquired ABCB1 promoter fusions previously unreported in breast cancer, potentially promoting drug resistance." (PMID 29093439, 2017). "A similar chemoresistant phenotype derived from ABC transporter overexpression is particularly relevant in breast cancer, where the first ABC transporter associated with chemoresistance was discovered (ABCB1/P-glycoprotein)." (PMID 28098760, 2017). "In fact, this metabolite extracted from the flowering plants Amaryllidaceae battles breast cancer, cervical cancer, and skin epidermoid carcinoma by inhibiting p-glycoprotein (P-gp) which is also known as the ABCB1-member of the ABC proteins." (PMID 28208712, 2017). "ABCB1 3435TT and ABCG2 421CC were significantly associated with longer PFS in Chinese breast cancer patients." (PMID 29340035, 2017). "Our results showed that breast carcinoma patients with ABCB1 3435TT genotype had significantly longer PFS than those with CC genotype." (PMID 29340035, 2017). "In all three breast cancer cell lines investigated, the ABCB1 promoter was found to be highly methylated." (PMID 27689338, 2016). "In this study, we explored the effect of 2 common polymorphisms in ABCB1 (rs10276036 C/T) and SLC22A16 (rs12210538 A/G) on the development of grade 3/4 febrile neutropenia in Iranian breast cancer patients." (PMID 28036387, 2016). "A few papers indicate that hypermethylation of the ABCB1 promoter is a frequent event in breast cancer, so far data on promoter methylation of ABCC1 and ABCG2 has, however, not been published." (PMID 27689338, 2016). "In this study, we explored the role of ABCB1 (rs10276036 C/T) and SLC22A16 (rs12210538 A/G) gene polymorphisms in the development of grade 3/4 febrile neutropenia in Iranian breast cancer patients who were administered DOX-based chemotherapy." (PMID 28036387, 2016). "In one study, amplification of the ABCB1 gene was observed after exposures to doxorubicin, colchicine, vinblastine or vincristine in epidermoid carcinoma, colon carcinoma, breast carcinoma and lymphoma cell lines." (PMID 29061940, 2015). "Doxorubicin and paclitaxel, which are commonly used in treating breast cancer, are all ABCB1 substrates." (PMID 26036634, 2015). "In human medicine, an inverse correlation has been observed between DNA methylation rates in the promoter region and ABCB1 mRNA expression levels in T-cell leukemia, breast cancer and other tumor cell lines." (PMID 29061940, 2015). "P-glycoprotein (P-gp, P170), encoded by the MDR1 gene (ABCB1) in humans is the major cause of multidrug resistance in breast cancer." (PMID 24456584, 2014). "Type 1 cAMP-dependent Protein Kinase A-related pathway is one of the pathways that modulates ABCB1 expression in multidrug-resistant breast cancer cells." (PMID 25401518, 2014).
breast carcinoma (continued). "Towards this goal, expression of Wnt5A and ABCB1 in biopsies from 24 pre-and post-chemotherapeutic-treated breast cancer patients were analyzed." (PMID 25401518, 2014). "Analogously with the ABCB1/P-glycoprotein, in the present study, we have observed associations between genetic variability in ABCC1 and its transcript levels in tissues from breast cancer patients." (PMID 25078270, 2014). "The dependence of ABCB1 expression on β-catenin signalling was also reported for breast cancer cells." (PMID 22460269, 2012). "In addition, upregulation of ABCB1 genes encoding the P-glycoprotein drug efflux pump has been found to be responsible for acquired resistance in a genetically engineered mouse model (GEMM) for BRCA1-associated breast cancer, following prolonged exposure to olaparib." (PMID 22481932, 2012). "Elsewhere, β-AR agonists such as epinephrine have been previously reported to induce resistance to paclitaxel in MCF-7 breast cancer cells and to 5-FU in HT-29 colon cancer cells through up-regulation of the ABCB1 gene." (PMID 22006582, 2011). "Variant alleles in the ABCB1, SLC22A16 and CYP2B6 genes are associated with response to AC therapy in the treatment of breast cancer." (PMID 20179710, 2010). "Breast cancer specific survival was significantly improved in patients with methylated promoters for ABCB1, GSTP1 and FOXC1 (p = 0.004, p = 0.004 and p = 0.021 respectively)." (PMID 20338046, 2010). "The potential regulatory mechanism by which the FTH1P3 influences paclitaxel resistance in breast cancer, through its involvement with the miR-206/ABCB1 pathway, provides a new view that could lead to advancements in breast cancer chemotherapy." (PMID 41362671, 2026). "In breast cancer, ABCB1 expression may be intrinsically elevated, particularly in aggressive subtypes such as TNBC, or induced by chemotherapeutic pressure." (PMID 40806254, 2025). "ABCB1 is one of these genes that encodes P-glycoprotein (P-gp), an ATP-binding cassette (ABC) efflux transporter involved in multidrug resistance (MDR) in breast cancer, which expels chemotherapeutic drugs from cells, reduces drug efficacy, and contributes to treatment failure." (PMID 41378310, 2025). "To further validate these findings, we analyzed MCF‐7 and MCF‐7/ABCB1 breast cancer cells." (PMID 41189280, 2025). "ABCB1 also mediates PARPi resistance in ovarian and breast cancers." (PMID 41357999, 2025). "Studies report that MPs can upregulate efflux transporters (ABCB1/ABCG2) and alter chemotherapeutic susceptibility, enhance metastatic features in breast cancer, promote therapy resistance via ASGR2 in gastric cancer, and aggravate radiation-induced intestinal injury." (PMID 41378310, 2025). "For example, NF‐κB signaling inhibitors downregulated ABCB1 expression in breast cancer cells." (PMID 39372126, 2024). "Similarly, paclitaxel and docetaxel are also responsible for an increased expression of ABCC2 and ABCB1 genes in breast cancer." (PMID 38534323, 2024). "Previous studies have highlighted the potential of bufalin in increasing the sensitivity of cancer cells to targeted therapy, particularly sorafenib in hepatocellular carcinoma and MEKi in leukemia, as well as in reversing ABCB1-mediated resistance to docetaxel in breast cancer." (PMID 38178183, 2024). "ABCB1 is ubiquitously present among LC, ovarian cancer, breast cancer, glioblastoma and renal cancer, and it is responsible for promoting tumour chemoresistance to drugs, such as, anthracycline actinomycin D, cisplatin, colchicine, etoposide, teniposide, methotrexate and others." (PMID 38396325, 2024). "Furthermore, the transcription factor C/EBP-β was found to activate ABCB1/P-glycoprotein in breast cancer cells." (PMID 38473345, 2024).
breast carcinoma (continued). "Huang and colleagues have shown that the lncRNA EPB41L4A-AS2 was downregulated in docetaxel-resistant MDA-MB-231 and MCF-7 breast cancer cells, and lower EPB41LA4-AS2 expression was associated with the upregulation of ABCB1 and the promotion of docetaxel resistance in breast cancer cells." (PMID 37104009, 2023). "Importantly, ABCB1/ABCG2 inhibitor dofequidar improved therapy responses in a subset of breast cancer patients." (PMID 37147730, 2023). "It is believed that a decrease in the ABCB1 gene expression in breast cancer cells may be a consequence of genomic instability in cancer cells, especially in triple-negative breast cancer." (PMID 36674773, 2023). "The ABCB1 gene was reported to be up-regulated in multidrug resistant (MDR) breast cancer cells." (PMID 36867605, 2023). "Lapatinib (Tykerb), a dual tyrosine kinase inhibitor that interrupts the HER2/neu and epidermal growth factor receptor (EGFR) pathways, was approved for the use of breast cancer and other solid tumors, and was also shown to inhibit ABCB1- and ABCG2-mediated MDR in cancer cells." (PMID 35327403, 2022). "However, previous studies in breast cancer have shown a higher doxorubicin clearance and lower peak levels of doxorubicinol with the wild-type haplotype of ABCB1." (PMID 35456712, 2022). "Breast cancer specimens with high STAT5a expression showed high ABCB1 expression levels." (PMID 34336684, 2021). "Hence, BPD is a promising agent to incorporate in a photoimmunoconjugate formulation for diagnosis of ABCB1 expression in breast cancer." (PMID 35070633, 2021). "In our study, pimozide inhibited STAT5a and ABCB1 in a dose-dependent manner and sensitized breast cancer cells to DOX, which could be rescued by overexpression of STAT5a or ABCB1." (PMID 34336684, 2021). "Subsequently, a rescue experiment was performed to confirm whether STAT5a modulates chemoresistance in breast cancer cells by regulating ABCB1." (PMID 34336684, 2021). "STAT5a confers breast cancer chemoresistance by upregulating the transcription of ABCB1." (PMID 34336684, 2021). "Main mechanism of drug resistance for chemotherapy of breast cancer is plasma membrane transporters, including P-glycoprotein (Pgp/ABCB1) and MDR-related proteins (MRPs/ABCC), can actively transport chemotherapy drugs to the extracellular space, ultimately reducing intracellular concentrations." (PMID 34696661, 2021). "Besides, the detection of ABCB1 in breast carcinoma also needs to be compared with its expression in normal mammary tissues adjacent to tumour area, especially considering the high prevalence of ABCB1 expression in breast tissue." (PMID 33801148, 2021). "Similarly, Mechetner and Kyshtoobayeva found that the expression of ABCB1 was strongly correlated with doxorubicin and Taxol resistance in vitro by using patient-derived breast cancer cells." (PMID 33801148, 2021). "This review summarises the structure, clinical insights and pharmacokinetics and drug-resistant functions of the most representative ABC transporter, ABCB1, in breast cancer and further discusses the role of ABC transporters in breast cancer progression and metastasis." (PMID 33801148, 2021). "Relevant studies have shown that chromosome 7q11.2–21 is amplified and the ABCB1 gene encoding P-gp is fused with the transcription of the upstream gene SLC25A40, which leads to the overexpression of P-gp and causes breast cancer cells to develop drug resistance." (PMID 34502549, 2021). "The drug efflux pump ABCB1 plays a key role in chemoresistance by effluxing various chemotherapeutic agents from tumor cells, and its expression is negatively correlated with the prognosis of cancers, including that of breast cancer." (PMID 34336684, 2021). "Thus, ABCB1 is essential to chemoresistance in breast cancer cells by pumping drugs out of cancer cells." (PMID 34336684, 2021).
breast carcinoma (continued). "In addition, gene rearrangements that fuse the ABCB1 gene with an aberrant active promoter that drives its expression, have been observed in ovarian cancer, lymphoma and breast cancer." (PMID 31530935, 2020). "In addition, ABCB1 methylation was lower in highly proliferative tumors, suggesting a role for ABCB1 methylation in breast cancer progression and outcome." (PMID 33066132, 2020). "Here we identify ROR1 as a key upstream regulator of ABCB1 and chemoresistance in breast cancer." (PMID 32020017, 2020). "However, only T47DOE cells had an increase in MDR1 (P-gp/ABCB1/MDR1), associated with chemoresistance to taxanes and anthracyclines, and poor outcomes in breast cancer." (PMID 32477461, 2020). "Similar differences were observed for the breast cancer risk gene ABCC11 (1.8 in East Asians compared to 0.5 in Africans), as well as the multi-drug resistance genes ABCB1 (1.4 in South Asians compared to 0.2 in Africans) and ABCG2 (1.3 in East Asians compared to 0.1 in Europeans)." (PMID 32206879, 2020). "ABCB1 is expressed in 28% to 63% of breast cancers, depending on the methodology applied." (PMID 32080081, 2020). "With the aim to identify a DNA methylation based biomarker to stratify breast cancer patients for neoadjuvant treatment with doxorubicin, the methylation status in the promoter regions of 14 genes including ABCB1 has been determined in 75 samples from locally advanced breast cancer." (PMID 33066132, 2020). "In addition, hypomethylation of the ABCB1 promoter in the MDR phenotype of breast cancer has been reported in four out of six studies." (PMID 33066132, 2020). "Moreover, many cancers are characterized by overexpression of ABCB1, including thyroid cancer, lung cancer, breast cancer, chronic myeloid leukemia, ependymoma, and osteosarcoma." (PMID 32428872, 2020). "Similarly, CRISPR has been evaluated to increase chemosensitivity in breast cancer by inactivating or down-regulating the MDR1 gene (also known as ABCB1) that significantly increased the doxorubicin cytotoxicity in resistant chemotherapy breast cancer cells." (PMID 33614489, 2020). "Nevertheless, the underlying mechanism responsible for the altered expression of both miR-203 and miR-200c and ABCB1 in doxorubicin resistance breast cancer and their specific role and mechanism of modulation of the activity of the ABCB1 efflux pump in drug resistance, still need to be elucidated." (PMID 35582584, 2019). "In the present study, we investigated the pharmacokinetics profile and the influence of CYP2D6, CYP2C9, CYP2C19, CYP3A5, POR, ABCB1 and UGT2B15 polymorphisms on the plasma level of tamoxifen and its active metabolites in Ethiopian breast cancer patients receiving adjuvant tamoxifen." (PMID 31547390, 2019). "Furthermore, AESN downregulated the expression of gene ABCB1, which encodes multidrug resistance protein 1 (MDR1), an important efflux pump in generating drug resistance in breast cancer treatment." (PMID 31835887, 2019). "Toosendanin down-regulated ABCB1 mRNA expression level under 48 h treatment in resistant breast cancer cell MCF-7/ADM, whereas sipholane A 72 h treatment exhibited no influence on P-gp expression level in drug-resistant human colon cancer cell line SW620/Ad300." (PMID 31766413, 2019). "There is growing evidence that altered ABCB1 activity may affect tamoxifen pharmacokinetics and possibly tamoxifen efficacy in breast cancer patients." (PMID 31547390, 2019). "In conclusion, this exploratory study is the first to show effect modifications between the ABCB1 C3435T genotype and preoperative statin use on breast cancer outcomes, including breast cancer-free and distant metastasis-free intervals, and most importantly, overall survival." (PMID 30370250, 2018). "The results must therefore be viewed with caution and confirmatory studies are warranted to elucidate whether there is a true effect modification by the ABCB1 C3435T genotype on statin in relation to breast cancer outcomes." (PMID 30370250, 2018).
breast carcinoma (continued). "Similarly,CROThas been shown to be co-amplified with ABCB1 in taxaneresistantovarian and breast cancers." (PMID 31223218, 2018). "No clear association was found when breast cancer-free interval was compared across the different ABCB1 genotypes (TT, CT, and CC) (Log-Rank, 2 d.f., P = 0.13)." (PMID 30370250, 2018). "Compared with previous studies, we discovered several novel genes in addition to ABCB1 which might contribute to the taxane-resistant phenotype of breast cancers." (PMID 30568280, 2018). "Since this is an exploratory study of the impact of the ABCB1 genotype in relation to statin use and clinical outcomes in the breast cancer setting, the results should be interpreted with caution and warrant replication in an independent cohort, preferably in a randomized setting." (PMID 30370250, 2018). "However, a high mutation rate of both ABCB1 C3435T and ABCG2 C421A (16% and 17%, respectively) was observed in breast cancer tissues." (PMID 29340035, 2017). "In addition, we found that exogenous expression of ΔNp73 led to an increase in the expression of ABCB1 and ABCB5 in the breast cancer-derived cell lines tested, while knocking down of ΔNp73 resulted in a reduction in ABCB1 and ABCB5 expression." (PMID 28677036, 2017). "To further examine the involvement of ABCB1 and ABCC11 in the development of eribulin resistance in breast cancer cells, we tested whether knockdown of ABCB1 or ABCC11 would restore eribulin sensitivity in eribulin-resistant breast cancer cells." (PMID 27588398, 2016). "Furthermore, Bray and colleagues studied the association of polymorphic variants of the ABCB1 and SLC22A16 genes with drug toxicity in breast cancer patients treated with DOX, and found that polymorphisms are associated with the development of toxicities." (PMID 28036387, 2016). "Moreover, analysis of the data from TCGA database revealed that MRP1 expression level in breast cancer samples was higher than that of most other ABC transporters, such as ABCB1 and ABCG2, which are reported to be associated with drug resistance." (PMID 27487127, 2016). "Moreover, lapatinib given in combination with tamoxifen (substrate of ABCB1) was also found to effectively inhibit cell proliferation and restore tamoxifen sensitivity in ER-positive and tamoxifen-resistant breast cancer." (PMID 26036634, 2015). "However, clinical studies revealed a positive correlation between ABCB1 expression and poor prognosis in breast cancer, sarcoma and certain types of leukemia, because ABCB1-positive biopsies from these cancers can be compared with ABCB1-negative patients." (PMID 26431273, 2015). "Both proteins are predominantly located in the Lubrol-based detergent-insoluble glycosphingolipid-enriched membrane domains and co-immunoprecipitation assays confirm that Cav-1 interacts with ABCB1 in brain capillaries, rat brain endothelial, Chinese hamster ovary and breast cancer cells." (PMID 26431273, 2015). "Similarly, an ABCB1 promoter hypermethylation was shown in MCF-7 human breast cancer cells and in human prostate cancer compared with benign prostate hypertrophy." (PMID 24380367, 2013). "ABCB1 was also induced by the SXR agonist rifampicin in breast cancer cells." (PMID 23919967, 2013). "Indeed, Yamada and colleagues, Flahaut and colleagues and Bourguignon and colleagues revealed the involvement of the Wnt/β-catenin pathway in ABCB1 regulation in early colorectal cancer, neuroblastoma and breast cancer, respectively." (PMID 22823957, 2012).